FLAD1 (flavin adenine dinucleotide synthetase 1)
Description:
This enzyme has two activities: FAD diphosphatase activity and FAD synthase activity. FAD diphosphatase acts on FAD and NADH to produce FMN and NMNH(2-), respectively. FAD synthase catalyzes the adenylation of flavin mononucleotide (FMN) to form flavin adenine dinucleotide (FAD) coenzyme. In addition to its catalytic activities, the protein also facilitates the delivery of FAD to client apo-flavoproteins. The balance between FAD synthesis and hydrolysis may be regulated by redox-sensing cysteine residues. At a much lower rate, FAD synthase catalyzes the reverse pyrophosphorolytic reaction. FAD synthase can also convert roseoflavin mononucleotide (RoFMN) to roseoflavin adenine dinucleotide (RoFAD); RoFMN is produced by riboflavin kinase when acting on the antibiotic roseoflavin (RoF). FAD synthase cannot convert 8-demethyl-8-amino-riboflavin mononucleotide (AFMN) to 8-demethyl-8-amino-riboflavin adenine dinucleotide (AFAD); AFMN is produced by riboflavin kinase when acting on the antibiotic 8-demethyl-8-amino-riboflavin (AF).
Synonyms: PP591; FAD1; FADS; LSMFLAD
Tractability: Small molecule: a structure with a bound ligand is known. Antibody: its Gene Ontology location is reachable by antibodies, with high confidence. PROTAC: ubiquitination databases record sites on it; its protein half-life has been measured.
Target class: Enzyme; Transferase
Gene: Protein-coding gene on chromosome 1 (154,983,338 to 154,993,111, forward strand). Ensembl gene ENSG00000160688.
Subcellular location: Nucleus; Mitochondrion matrix (Isoform 1); Cytoplasm, cytosol (Isoform 2)
Subcellular location (Human Protein Atlas): Cytosol; Plasma membrane; Cytokinetic bridge; End piece; Mid piece; Primary cilium; Principal piece
Pathways (Reactome):
Metabolism: Vitamin B2 (riboflavin) metabolism
Gene Ontology:
Molecular function: FMN adenylyltransferase activity; identical protein binding; NADH pyrophosphatase activity; protein binding; catalytic activity; FAD diphosphatase activity
Biological process: FAD biosynthetic process; riboflavin metabolic process
Cellular component: cytosol; mitochondrial matrix; mitochondrion; cytoplasm; nucleus
Genetic constraint (gnomAD): Loss-of-function variants: 35 observed, 57.38 expected, observed/expected ratio (o/e) 0.61, 90% interval 0.47 to 0.81. The upper end of that interval is the gene's LOEUF score, 0.81, which puts it in group 3 of 6, group 1 being the genes least tolerant of losing a copy. Missense variants: 665 observed, 766.4 expected, observed/expected ratio (o/e) 0.87, 90% interval 0.81 to 0.93. Synonymous variants: 267 observed, 315.08 expected, observed/expected ratio (o/e) 0.85, 90% interval 0.77 to 0.94.
Gene-disease validity (ClinGen):
ClinGen rates the evidence that FLAD1 causes each of these diseases.
myopathy with abnormal lipid metabolism (autosomal recessive): Definitive.
Homologues: Orthologues: chimpanzee FLAD1 (99% identical), macaque FLAD1 (79% identical), rabbit FLAD1 (77% identical), dog FLAD1 (76% identical), rat Flad1 (75% identical), pig FLAD1 (75% identical), mouse Flad1 (75% identical), guinea pig FLAD1 (74% identical), zebrafish flad1 (46% identical), tropical clawed frog flad1 (45% identical), Caenorhabditis elegans flad-1 (32% identical), Drosophila melanogaster Flad1 (17% identical), and 1 more.
Diseases named in the same sentence as FLAD1 in open-access papers:
FLAD1 is named in the same sentence as 41 diseases in open-access papers, as found by Europe PMC text mining. Sharing a sentence is not in itself a finding about the gene and the disease. The quoted sentences say what the papers report.
multiple acyl-CoA dehydrogenase deficiency (4 papers, 2018 to 2025). "One child affected with both CPT2 and MAD deficiencies was also identified, caused by bi-allelic variants in both CPT2 and FLAD1." (PMID 40981303, 2025). "Multiple acyl-CoA dehydrogenase deficiency (MADD) also known as glutaric academia type II or lipid-storage myopathy—is caused by loss-of-function variants in ETFDH, ETFA, ETFB or, more rarely, FLAD1." (PMID 40963932, 2025). "This isoform has been previously detected in Riboflavin-Responsive (RR-MADD) and Non-responsive Multiple Acyl-CoA Dehydrogenase Deficiency (MADD) patients with frameshift mutations of FLAD1 gene." (PMID 29316637, 2018).
hepatocellular carcinoma (3 papers, 2020 to 2025). A malignant tumor that arises from hepatocytes. "The overexpression of FLAD1 has been reported in various cancers such as hepatocellular carcinoma, gastric cancer, and breast cancer." (PMID 34336008, 2021). "The FLAD1 expression was previously reported to be upregulated in hepatocellular carcinoma and is considered to be related to hepatitis B virus infection." (PMID 34336008, 2021).
lipid storage myopathy (3 papers, 2019 to 2025). "Furthermore, FLAD1 deficiency leads to lipid storage myopathy, demonstrating its involvement in mitochondrial dysfunction." (PMID 41235234, 2025).
bladder cancer (2 papers, 2021 to 2022). "Then, 9 target genes that were differentially expressed between bladder cancer and normal samples were screened (FDR < 0.05), in which upregulated expression of RHBG, PAQR6, CLK2, KRTCAP2, FLAD1, HCN3 were correlated with bad survival of patients with bladder cancer." (PMID 36186809, 2022).
gastric cancer (2 papers, 2020 to 2021). A primary or metastatic malignant neoplasm involving the stomach. "The FLAD1 expression has also been shown to be upregulated in gastric cancer and breast cancer." (PMID 34336008, 2021).
liver cancer (2 papers, 2021 to 2025). An epithelial or non-epithelial malignant neoplasm that arises from the liver. "These comprehensive analyses from our in-house cohort confirm the role of FLAD1 as a critical biomarker in HCC, highlighting its potential clinical significance in the context of liver cancer diagnostics and treatment planning." (PMID 41235234, 2025).
breast carcinoma (1 paper, 2021). "In previous studies, the FLAD1 expression was found to be linked to let-7b with respect to tumorigenesis in breast cancer, based on the analysis of somatic single-nucleotide variants and miRNA–mRNA pairs." (PMID 34336008, 2021). "In this study, we explored the diagnostic and prognostic value of the FLAD1 expression across pan-cancer analysis from online databases (Oncomine, cBioPortal, Breast Cancer Gene-Expression Miner, UALCAN, GEO, BCIP, TNMplot, ENCORI, Kaplan-Meier Plotter, and LinkedOmics)." (PMID 34336008, 2021). "In this study, we analyzed the transcription levels of FLAD1 in pan-cancer analysis with a focus on breast cancer and further classified the results on the basis of the clinicopathologic parameters." (PMID 34336008, 2021). "We used cBioPortal to determine the type and frequency of FLAD1 alterations in 106 of 996 patients with breast cancer." (PMID 34336008, 2021). "We first analyzed the FLAD1 expression in human cancers and found that it was overexpressed in six breast cancer datasets in the Oncomine database." (PMID 34336008, 2021). "Therefore, in this study, we searched for relevant data from online databases to determine the diagnostic and prognostic value of the abnormal expression of FLAD1 and related miRNAs in pan-cancer analysis, especially in breast cancer." (PMID 34336008, 2021). "Amplification was the most frequent FLAD1 alteration type identified in breast cancer." (PMID 34336008, 2021). "We also analyzed the FLAD1-related microRNAs and their prognostic values in breast cancer." (PMID 34336008, 2021). "Thus, amplification may be the most common type of FLAD1 alteration in breast cancer." (PMID 34336008, 2021).
breast invasive carcinoma (1 paper, 2021). "UALCAN was also used to reveal the clinical parameters related to FLAD1 in breast invasive carcinoma." (PMID 34336008, 2021).
diabetes (1 paper, 2020). "For instance, target genes (FLAD1, SLFNL1, GNS, FBXL18, CYP2B7P) are commonly upregulated genes in metabolic-induced HCC and are associated with risk factors, such as diabetes, obesity, and other metabolic syndromes." (PMID 32228601, 2020).
metabolic myopathies (1 paper, 2018). "No other causative mutations associated with metabolic myopathies or inherited neuropathies were found in the target gene kits including the ETFA, ETFB, flavin adenine dinucleotide synthetase 1 (FLAD1), and solute carrier family 25 member 32 (SLC25A32) genes." (PMID 30587156, 2018).
Mitochondrial myopathy (1 paper, 2022). "Since the discovery of FLAD1 as a causing gene for the human severe mitochondrial myopathy, first classified as MADD, and recently named LSMFLAD,12, 13 the number of patients is rapidly increasing (see References 11, 12, 15, 16 for recent reviews)." (PMID 34558787, 2022).
tumor (7 papers, 2020 to 2025). "The dysregulation of this FLAD1-associated metabolic network reinforces its role in fueling the bioenergetic needs for tumor proliferation and survival." (PMID 41235234, 2025). "Due to its function in the oxidation-reduction chain, FLAD1 is strongly associated with the survival of malignant tumor cells and thus the prognosis of malignant tumor." (PMID 32714079, 2020). "Further, hsa-miR-532-3p along with hsa-miR-139 are associated with CHRD, FLAD1, MT1JP, and EBF2 in our analysis and have been identified as tumor suppressors in HCC that inhibit cell proliferation, migration, and invasion." (PMID 32228601, 2020). "This analysis also validated FLAD1 upregulation within the spatial context of the tumor." (PMID 41235234, 2025). "These discoveries imply that FLAD1 may modulate the tumor microenvironment, potentially creating a more immunosuppressive environment that facilitates tumor growth and progression." (PMID 41235234, 2025). "SREBP1 expression is upregulated in TNBC through several pathways, including the FLAD1/LSD1 axis and the mTORC1 signaling pathway, both of which enhance lipid biosynthesis and support tumor progression." (PMID 40427160, 2025). "Key clinical characteristics, including FLAD1 expression, stage III disease, and tumor status, were identified as independent predictors of OS in HCC patients." (PMID 41235234, 2025). "FLAD1, located at chromosome region 1q21.3, is frequently amplified in TNBC, contributing to poor prognosis by driving tumor progression." (PMID 40427160, 2025). "One of the genes, FLAD1 showed upregulated expression in both HCC tissues compared to healthy liver samples and in HCC tissues relative to paired adjacent non-tumor tissues." (PMID 41235234, 2025). "Crucially, our analysis confirmed that this entire 20-gene functional network is differentially expressed in high-FLAD1 HCC, indicating that these gene-gene interactions are not only functionally linked but also empirically altered in the tumor context." (PMID 41235234, 2025). "Spatial feature plots confirmed that FLAD1 was expressed within the tumor regions of both the encapsulated and non-encapsulated samples." (PMID 41235234, 2025). "FLAD1, which shows favourable prognostic features along with positive correlation with TPS, is essential for vitamin B2 (riboflavin) metabolism, facilitating mitochondrial function and the high energy demands of tumour cells energy demands." (PMID 39457550, 2024). "The sex, tumor size, tumor grade, metastasis, infiltration status and Ki-67 expression level were not of significant difference between the FLAD1-positive and the FLAD1-negative group, though the majority of patients had pT3 disease (79.2%)." (PMID 32714079, 2020). "However, the sex, tumor size, tumor grade, metastasis, and infiltration status were not of significant difference between the FLAD1-positive and the FLAD1-negative group." (PMID 32714079, 2020).
cancer (5 papers, 2020 to 2025). A tumor composed of atypical neoplastic, often pleomorphic cells that invade other tissues. "Therefore, further research is needed to validate the results of this study and elucidate the biological mechanism underlying the role of FLAD1 in cancers." (PMID 34336008, 2021). "Recently researchers have started to investigate the association between FLAD1 and cancer." (PMID 32714079, 2020). "Preliminary studies have indicated FLAD1’s involvement in tumorigenesis and cancer advancement, making it a promising HCC therapeutic target for further investigation." (PMID 41235234, 2025). "Studies have shown that FLAD1 is highly amplified in pancreatic cancer and is overexpressed in various cancers, correlating with poor prognosis." (PMID 41235234, 2025). "In the present study, we found some FLAD1-related miRNAs, which showed significant differences in the cancer and normal samples, indicating their potential prognostic value." (PMID 34336008, 2021). "This study highlights the significance of FLAD1 in cancers and provides evidence for its potential as a biomarker for the diagnosis and prognosis of cancers." (PMID 34336008, 2021). "This study reports the significance of FLAD1 in cancer based on multilevel data in public databases and provides evidence for its potential as a biomarker for the diagnosis and prognosis of various cancers." (PMID 34336008, 2021). "FLAD1 has recently emerged as a potential player in cancer progression." (PMID 41235234, 2025). "In cancer, FLAD1 has emerged as a promising therapeutic target." (PMID 41235234, 2025). "We also found some evidence for the abnormal expression of FLAD1 in various cancers in ENCORI." (PMID 34336008, 2021). "Further research on the possibility of the application of FLAD1 as a therapeutic target based on small-molecule probes has yielded initial results, indicating that FLAD1 also has certain potential as a target for cancer treatment." (PMID 34336008, 2021). "Based on these relationships, it could be hypothesized that FLAD1 may participated in cancer cell proliferation, migration and DNA damage repair." (PMID 32714079, 2020). "It remains ambiguous how the FLAD1 exerts unique impact on cancer development." (PMID 32714079, 2020). "Coexpression analysis revealed that FLAD1 is coupregulated with other genes in HCC, suggesting potential interactions in cancer development." (PMID 41235234, 2025). "In our study, HAX1, FLAD1 and NDUFS2, which were positively correlated with DAP3, were reported to play a crucial in mitochondria which could regulate the progression in numerous cancers, indicating that DAP3 may be an important role in OXPHOS, which could affect HCC progression." (PMID 40051634, 2025).
genetic disease (1 paper, 2021). "FLAD1 is related to the metabolism of water-soluble vitamins and cofactors, and FLAD1 mutations cause a FAD synthase deficiency, which is a rare genetic disease affecting mitochondrial energy metabolism and other riboflavin metabolism." (PMID 34336008, 2021).
metabolic disease (1 paper, 2019). A congenital disorder (due to inherited enzyme abnormality) or acquired (due to failure of a metabolically important organ) disorder resulting from an abnormal metabolic process. "Newborn screening, designed to screen for specific treatable congenital metabolic diseases, may also lead to the diagnosis of additional, very rare metabolic disorders such as FLAD1 deficiency." (PMID 31392824, 2019).
FLAD1 also shares sentences with these, for which no sentence is quoted: bladder urothelial carcinoma (1 paper); cardiomyopathy (1); cholangiocarcinoma (1); colon adenocarcinoma (1); colon cancer (1); esophageal cancer (1); head-neck squamous cell carcinoma (1); Infertility (1); lung adenocarcinoma (1); lung carcinoma (1); lung squamous cell cancer (1); metabolic syndrome (1); non-small cell lung carcinoma (1); Obesity (1); ovarian carcinoma (1); pancreatic cancer (1); prostate carcinoma (1); rectum cancer (1); sarcoma (1); skin cancer (1); stomach cancer (1); testicular cancer (1); thymoma (1); tuberculosis (1); uterine carcinosarcoma (1); uterine corpus endometrial carcinoma (1).